CYP2R1 (cytochrome P450 family 2 subfamily R member 1)
Diseases named in the same sentence as CYP2R1 in open-access papers (continued):
Sharing a sentence is not in itself a finding about the gene and the disease.
asthma (13 papers, 2006 to 2025). "SNPs in the CYP2R1 gene, encoding an enzyme implicated in earlier steps of the vitamin D metabolic pathway, were also associated with asthma in both the German and the SLSJ studies." (PMID 19852851, 2009). "For CYP2R1, two additional SNPs located in the promoter and intron 1 were associated with asthma in the BHS." (PMID 19852851, 2009). "Furthermore, both VDR and CYP2R1 polymorphisms have been reported to be correlated with susceptibility to other allergic diseases, such as asthma." (PMID 26177022, 2015). "Similarly, evidence for association between CYP2R1 variants and asthma has also been inconsistent between populations." (PMID 21810276, 2011). "Finally, one SNP (rs11023374) in intron 2 of the CYP2R1 gene was associated with asthma (p = 0.017)." (PMID 19852851, 2009). "We sequenced all 8 exons of VDR and all 5 exons of CYP2R1 in a Chinese case-control cohort of asthma consisting of 467 cases and 288 unrelated healthy controls." (PMID 21810276, 2011). "SNPs located in five genes, including IL10, CYP24A1, IL1RL1, CYP2R1 and CD86, showed modest association with asthma or atopy in an asthma family study derived from the Saguenay_Lac-Saint-Jean population." (PMID 19852851, 2009). "A number of SNPs in the IL10, CYP24A1, CYP2R1, IL1RL1 and CD86 genes were modestly associated with asthma and atopy (p < 0.05)." (PMID 19852851, 2009). "In our study, the presence of CYP2R1 rs10741657 was not related to a higher risk of suffering from asthma." (PMID 36839181, 2023). "SNPs in the vitamin D pathway (CYP27A1, CYP27B1, CYP2R1, CYP24A1, and GC) affecting 25OHD levels demonstrated moderate effects on risk of asthma in a prior adult study, but the role of these variants on asthma risk later in life is unknown." (PMID 28486474, 2017). "Alternative CYP2R1 variants have also been implicated in asthma susceptibility, though these effects have not replicated consistently among populations." (PMID 21810276, 2011). "In this study, we tested whether polymorphisms of genes encoding for vitamin D receptor (VDR), vitamin D 25-hydroxylase (CYP2R1) and vitamin D binding protein (GC) were associated with asthma in the Chinese Han population." (PMID 21810276, 2011). "In this study we set out to evaluate whether the variants of genes encoding for the key components of vitamin D pathway, including CYP2R1, VDR, and DBP, were associated with asthma or asthma-related phenotypes in a case-control design study in the Chinese Han population." (PMID 21810276, 2011). "CYP2R1 activity has been shown to be impaired in several animal models and has also been confirmed in COPD and asthma patients." (PMID 34064175, 2021). "Similar to the previous analysis for asthma, we undertook sensitivity analyses by excluding the DHCR7 SNP to control for possible population stratification and by removing the CYP2R1 SNP, because of potential pleiotropy, and the results were similar." (PMID 28486474, 2017). "Another study reported an association between a CYP2R1 variant and FEV1 in children, and between specific haplotypes on CYP2R1 and CYP27A1 and asthma phenotypes." (PMID 28486474, 2017). "At least one positive SNP with a TDT of p < 0.05 for asthma or total IgE and calcidiol or calcitriol was seen in IL10, GC, IL12B, CYP2R1, IL4R, and CYP24A1." (PMID 16600026, 2006). "Therefore, we performed sensitivity analyses excluding the CYP2R1 and CYP24A1 SNPs (rs10741657 and rs6013897, respectively) from our MR instruments in our asthma analysis and excluding the CYP2R1 SNP (rs10741657) in our atopic dermatitis and IgE analysis." (PMID 28486474, 2017). "Variants in CYP2R1, CYP27B1 and CYP24A1 or other genes in the metabolic pathway of vitamin D have not been tested so far with asthma or allergy but several of the VDR-controlled genes tested here already have been associated with asthma and allergy." (PMID 16600026, 2006).
asthma (continued). "To assess the effect of the independent vitamin D pathways on risk of asthma, we analyzed SNPs near genes implicated in 25OHD synthesis (DHCR7 and CYP2R1) and metabolism (GC and CYP24A1) separately and found that none were associated with increased risk of asthma." (PMID 28486474, 2017).
type 1 diabetes (12 papers, 2012 to 2024). "It has been reported that CYP2R1 GG or CYP27B1 CC genotype carriers were associated with the increased type 1 diabetes progression." (PMID 35366956, 2022). "There was increased risk of type 1 diabetes for the GG genotype of CYP2R1 among subjects with CC genotype of CYP27B1." (PMID 35366956, 2022). "In a previous study, Nam et al18 showed that the CYP2R1 rs12794714 GG genotype and CYP2R1 rs10766196 AA genotype were associated with the risk of developing type 1 diabetes in Korean children." (PMID 33058307, 2021). "A recent study in the Korean population showed an association between CYP2R1 variants and type 1 diabetes." (PMID 32764491, 2020). "Of note, genetically variants in DHCR7 and CYP2R1 have previously been demonstrated to be associated with increased risk of type 1 diabetes." (PMID 31660975, 2019). "For example, SNPs in NAD synthetase 1/ 7-dehydrocholesterol reductase (NADSYN1/DHCR7) gene locus and SNPs in CYP27B1, CYP2R1 genes and have been associated with type 1 diabetes or with type 1 diabetes related autoantibodies." (PMID 28976992, 2017). "Nam et al18 hypothesized that the CYP2R1 rs12794714 and rs10766196 variants, both located at the CpG island, may modulate the gene transcription and were associated with the risk of developing type 1 diabetes." (PMID 33058307, 2021). "Alleles of DHCR7, GC, CYP2R1, and CYP24A1 play a synergistic role in susceptibility to type 1 diabetes by functioning in the vitamin D pathway and serum vitamin D levels." (PMID 38650715, 2024). "In 612 infants, we genotyped single nucleotide polymorphisms in vitamin D metabolism genes that relate with type 1 diabetes: rs10741657 and rs12794714 in CYP2R1, rs12785878 in DHCR7, and rs10877012 in CYP27B1." (PMID 37170809, 2023). "Another similar study showed a cumulative effect of SNPs at the CYP2R1 (rs2060793), DHCR7 (rs12785878), GC (rs2282679), and CYP24A1 (rs6013897) loci on the susceptibility to type 1 diabetes." (PMID 36090587, 2022). "We specifically studied the effect of a mouse model of type 1 diabetes on the regulation of Cyp2r1 and vitamin D status." (PMID 35524739, 2022). "In conclusion, our data suggest a synergistic effect of multiple alleles at the DHCR7, GC, CYP2R1 and CYP24A1 loci on the susceptibility to type 1 diabetes, due to the role of these genes in the vitamin D pathway and their effect on serum vitamin D levels." (PMID 32764491, 2020). "Nevertheless, the combined number of DHCR7, GC, CYP2R1 and CYP24A1 minor alleles that each individual harboured was associated with the risk of type 1 diabetes in our population." (PMID 32764491, 2020). "Genetic studies of type 1 diabetes pinpointed susceptibility single nucleotide polymorphisms (SNPs) mapped to genes in the vitamin D metabolism milieu, namely synthesis (DHCR7) and hydroxylation (CYP2R1, CYP27B1)." (PMID 37170809, 2023). "The aim of this study was to evaluate whether the DHCR7 rs12785878, GC rs2282679, CYP2R1 rs2060793 and CYP24A1 rs6013897 SNPs are associated with the susceptibility to type 1 diabetes in the Portuguese population." (PMID 32764491, 2020).
colorectal cancer (8 papers, 2016 to 2025). A primary or metastatic malignant neoplasm that affects the colon or rectum. "In this context, we conducted this study to examine the association between methylation levels of four vitamin D metabolic pathway-related genes (VDR, CYP24A1, CYP27B1 and CYP2R1) from blood and the risk of colorectal cancer." (PMID 37644572, 2023). "The methylation status of the CYP2R1 at all CpG sites was inversely associated with colorectal cancer risk, with an adjusted OR (aOR) of 0.49 (95% CI, 0.26–0.91; P = 0.02) comparing the hypermethylation with hypomethylation of the CYP2R1 gene." (PMID 37644572, 2023). "The cumulative methylation level of all CpG sites in CYP2R1 was inversely associated with the risk of colorectal cancer (aOR, 0.49; 95% CI, 0.26–0.91)." (PMID 37644572, 2023). "This study indicated that the cumulative methylation levels of significant CpG sites in VDR and CYP24A1 and all CpG sites in CYP2R1 were inversely associated with colorectal cancer risk." (PMID 37644572, 2023). "The results showed an inverse association between cumulative methylation levels of all CpG sites in CYP2R1 and colorectal cancer risk." (PMID 37644572, 2023). "Our study found that higher cumulative methylation level of all CpG sites in CYP2R1 was associated with a reduced risk of colorectal cancer." (PMID 37644572, 2023). "The cumulative methylation levels of significant CpG sites in VDR and CYP24A1 and all CpG sites in CYP2R1 were inversely associated with colorectal cancer risk." (PMID 37644572, 2023). "Heterozygote carriage of CYP2R1/rs10741657 was associated with a 12% decrease in colorectal cancer risk per 3 μg vitamin D ingested per day (IRR = 0.88, 95% CI: 0.79–0.97)." (PMID 32012190, 2020). "Incidence rate ratios were estimated by the Cox proportional hazards model, and interactions between polymorphisms in GC and CYP2R1 and vitamin D intake in relation to risk of colorectal cancer were assessed." (PMID 32012190, 2020). "The slopes of the curves describing the relationship between vitamin D intake and colorectal cancer risk for carriers of the different genotypes, were only significantly different from each other for CYP2R1/rs10741657 (p for interaction (pint) = 0.04)." (PMID 32012190, 2020). "On the other hand, we found interaction between CYP2R1/rs10741657 and vitamin D intake in relation to risk of colorectal cancer." (PMID 32012190, 2020). "For CYP2R1, although only one CpG site was significantly different between cases and controls, there was an inverse association between cumulative methylation levels of all CpG sites in CYP2R1 and colorectal cancer risk." (PMID 37644572, 2023). "Moreover, CYP2R1 rs12794714-A allele had correlation with a lower risk of colorectal cancer." (PMID 34093899, 2021). "The intensity of immunostaining was significantly higher in primary colorectal cancer compared with normal colonic mucosa for CYP2R1 (p<0.001), CYP7B1 (p<0.001), CYP8B1 (p<0.001), CYP46A1 (p<0.001) and CYP51A1 (p=0.001)." (PMID 27341022, 2016). "Immunohistochemistry was performed on a colorectal cancer tissue microarray containing 650 primary colorectal cancers using monoclonal antibodies to CYP2R1, CYP7B1, CYP8B1, CYP27A1, CYP39A1, CYP46A1 and CYP51A1, which we have developed." (PMID 27341022, 2016). "We hypothesized that the methylation level of CYP24A1 could be negatively associated with colorectal cancer risk, while the methylation levels of VDR, CYP2R1 and CYP27B1 could be positively associated with colorectal cancer risk." (PMID 37644572, 2023). "However, for colorectal cancer, two SNPs, rs12794714 (CYP2R1) and rs10741657 (CYP2R1) had nominally significant associations (HR (95% CI), p-values-rs12794714: 1.21 (1.03–1.41), p = 0.02 and rs10741657: 1.22 (1.05–1.43), p = 0.01)." (PMID 29315215, 2018).
colorectal cancer (continued). "By using quantitative real‐time polymerase chain reaction (qRT‐PCR), we analyzed the expression ratio of CYP2R1, CYP27A1 and CYP27B1 genes within the vitamin D metabolic pathway in a total of 75 colorectal cancer (CRC) tissues compared to the adjacent tissues." (PMID 33058307, 2021). "The results indicated 2.3 and 2.7 upregulation of CYP2R1 and CYP27B1 genes in colorectal cancer tissues compared to the adjacent tissues, respectively." (PMID 33058307, 2021). "Overall, the results indicated that 2.3 and 2.7 upregulation of CYP2R1 and CYP27B1 genes in colorectal cancer tissues compared to the adjacent tissues, respectively." (PMID 33058307, 2021). "In comparison with our results, dysregulated expression of CYP2R1 and CYP27B1 genes had been shown in different types of cancer, including oral squamous cell carcinomas and colorectal cancer." (PMID 33058307, 2021). "This study has profiled the expression of the cholesterol metabolising enzymes CYP2R1, CYP7B1, CYP8B1, CYP27A1, CYP39A1, CYP46A1 and CYP51A1 in primary colorectal cancer tissue using a well-characterised cohorts of colorectal cancers." (PMID 27341022, 2016). "However, the cumulative methylation level of all CpG sites of CYP2R1 in the colorectal cancer cases was non-significantly lower than that in controls." (PMID 37644572, 2023). "Thus, the found interaction suggests that vitamin D intake is protective against colorectal cancer in individuals with genetically determined high CYP2R1 enzyme levels, but not among individuals with genetically determined low CYP2R1 enzyme levels." (PMID 32012190, 2020). "CYP2R1, CYP7B1, CYP8B1, CYP46A1 and CYP51A1 all showed significantly increased expression in primary colorectal cancer compared to normal colonic mucosa with CY7B1 demonstrating the highest proportion of strong immunoreactivity in colorectal cancer compared to all other enzymes studied." (PMID 27341022, 2016). "However, CYP2R1 (p=0.034), CYP8B1 (p=0.002), CYP39A1 (p<0.001), CYP46A1 (p<0.001) and CYP51A1 (p=0.001) each demonstrated significantly reduced expression in paired lymph node metastasis compared to Dukes C (stage 3) colorectal cancer." (PMID 27341022, 2016).
type 2 diabetes (7 papers, 2015 to 2025). "Thus, the effect of Cyp2r1 repression on 25-OH-D level appears to be different in type 1 and type 2 diabetes mouse models." (PMID 35524739, 2022). "Thus, although the models of type 1 and type 2 diabetes have similar effects of the Cyp2r1 expression, regulation of other CYP enzymes appear to be different, which may explain the observed difference in the vitamin D 25-hydroxylase activity." (PMID 35524739, 2022). "Prior studies have established associations between certain vitamin D pathway polymorphisms, particularly in GC (e.g., rs4588, rs7041, rs2282679) and CYP2R1 (e.g., rs10741657, rs12794714, rs1993116, rs10766197), and metabolic syndrome and type 2 diabetes mellitus (T2DM)." (PMID 40708646, 2025).
breast carcinoma (6 papers, 2015 to 2026). "Genomic studies identify the Cyp2r1 gene as located in the so-called SuperMam1 locus, which is a mammary tumor susceptibility locus in the BALB/cTrp53+/-strain (model of spontaneous breast cancer)." (PMID 33172201, 2020). "Variants in CYP2R1, CYP24A1, CYP27B1, and DBP have been reported to influence circulating 25(OH)D concentrations and provide evidence for a hypothesis that these polymorphisms may be associated with breast cancer risk by altering vitamin D metabolism and signaling." (PMID 42292230, 2026).
COVID-19 (6 papers, 2021 to 2024). A disease caused by infection with severe acute respiratory syndrome coronavirus 2. "Association has also been observed between severe COVID-19 and CYP2R1 GG genotype, previously related to decreased levels of 25OHD." (PMID 34150833, 2021). "Our results pointed out to DHCR7/NADSYN1 rs12785878 and CYP2R1 rs10741657 variants, both involved in vitamin D synthesis, as potential risk factors of severe COVID-19." (PMID 34150833, 2021). "Results of our study showed association of DHCR7/NADSYN1 rs12785878 and CYP2R1 rs10741657 variants with severe form of COVID-19 in adult patients." (PMID 34150833, 2021). "Our results indicated an association between severe COVID-19 and CYP2R1 GG genotype." (PMID 34150833, 2021). "COVID-19 patients were genotyped for variants in DHCR7/NADSYN1, GC, CYP2R1, VDR, PPCDC and DMGDH genes." (PMID 34150833, 2021). "Therefore, we evaluated genetic determinants of vitamin D (DHCR7/NADSYN1 rs12785878, GC rs2282679, CYP2R1 rs10741657, VDR rs2228570), zinc (PPCDC rs2120019) and selenium (DMGDH rs17823744) as risk factors for severe forms of COVID-19." (PMID 34150833, 2021). "However, no SNPs examined in gene CYP2R1 were associated with risk of critical COVID-19 condition." (PMID 34835935, 2021). "Our study indicated an association between DHCR7/NADSYN1 rs12785878 and CYP2R1 rs10741657 variants and the severity of COVID-19, but the variants GC rs2282679 and VDR rs2228570 were not linked to a higher risk of severe COVID-19 in adults." (PMID 34150833, 2021).
Hypertension (6 papers, 2014 to 2025). The presence of chronic increased pressure in the systemic arterial system. "An observational Danish study on 11,6655 white individuals, genotyped for genetic variants in DHCR7 and CYP2R1 affecting plasma 25(OH)D, found that low 25(OH)D concentrations were associated with a higher blood pressure and hypertension." (PMID 36358492, 2022). "Previously, genetic polymorphisms in CYP2R1 were associated with various CVD-related diseases, including myocardial infarction and stroke, type 2 diabetes, and hypertension." (PMID 34262949, 2021). "Furthermore, we observed that both the rs10741657 and rs2060793 polymorphisms of the CYP2R1 can significantly influence glucose metabolism, while the rs7975232 polymorphism of the VDR was significantly associated with the risk of hypertension." (PMID 36364874, 2022).
metabolic syndrome (6 papers, 2020 to 2025). A cluster of metabolic risk factors for CARDIOVASCULAR DISEASES and TYPE 2 DIABETES MELLITUS. "In particular, mechanistic studies exploring how CYP2R1 polymorphisms contribute to both vitamin D insufficiency and features of metabolic syndrome may reveal novel targets for intervention." (PMID 40710009, 2025). "The specific molecular mechanism by which dyslipidemia affects the expression of CYP2R1 is still unknown." (PMID 38354201, 2024).
liver disease (4 papers, 2013 to 2025). "Patients with hepatic diseases are largely accompanied by reduced liver CYP2R1 activities and thus lower blood vitamin D levels, so does those with genetical variants within the CYP2R1 locus." (PMID 37817192, 2023). "In this regard, our study also cannot fully rule out whether all investigated genes (CYP2R1, GC, DHCR7) have the same impact on progression to HCV-related HCC at different stages of liver disease or in populations of different ancestries." (PMID 23734184, 2013).
melanoma (4 papers, 2018 to 2024). A malignant, usually aggressive tumor composed of atypical, neoplastic melanocytes. "Cediranib treatment resulted, however, in an increase in mRNA level for CYP3A4 and CYP2R1 in melanoma cells pretreated with 1,25(OH)2D3 (p < 0.05 vs. control and vs. monotreatment, respectively)." (PMID 35004285, 2021). "Interestingly, the strongest decrease in the mRNA levels of CYP3A4 and CYP2R1 was observed in A375 melanoma cells treated with 21(OH)pD." (PMID 30200275, 2018). "Furthermore, the expression of vitamin D3-related genes was altered by vitamin D3 analogs, and the effects on the expression of VDR, RXR, PDIA3, CYP2R1 or CYP24A1 were stronger in WM98 melanoma cells in comparison to the A375 line." (PMID 30200275, 2018). "CYP11A1, CYP24A1, CYP27B1, CYP2R1, and CYP3A4 are expressed in WM98 and A375 human melanoma cell lines." (PMID 38672780, 2024). "The treatment of A375 melanoma with four vitamin D3 analogs (1,25(OH)2D3, calcipotriol and 21(OH)pD) decreased the expression of VDR, RXR, PDIA3, CYP2R1 genes." (PMID 30200275, 2018). "On the other hand, the expression of VDR and its splicing variants and other vitamin D related genes (RXR, PDIA3, CYP3A4, CYP2R1, CYP27B1, CYP24A1 and CYP11A1) was detected in WM98 and A375 melanomas with the transcript levels being modulated by vitamin D analogs." (PMID 30200275, 2018). "CYP27A1, CYP27B1, and CYP2R1 are involved in the activation of vitamin D, whereas CYP24A1 and CYP3A4 are responsible for the degradation of the active vitamin D. CYP24A1, the primary catabolic enzyme of calcitriol, is overexpressed in melanoma tissues and cells." (PMID 38672780, 2024).